NKX2-8 (NK2 homeobox 8)
Synonyms: NKX2H; NKX2.8; Nkx2-9
Tractability: Antibody: the Human Protein Atlas places it where antibodies can reach.
Gene: Protein-coding gene on chromosome 14 (36,580,004 to 36,582,614, reverse strand). Ensembl gene ENSG00000136327.
Subcellular location: Nucleus
Subcellular location (Human Protein Atlas): Nucleoplasm; Plasma membrane
Gene Ontology:
Molecular function: DNA-binding transcription activator activity, RNA polymerase II-specific; DNA-binding transcription factor activity; double-stranded DNA binding; RNA polymerase II cis-regulatory region sequence-specific DNA binding; sequence-specific DNA binding; sequence-specific double-stranded DNA binding; DNA-binding transcription factor activity, RNA polymerase II-specific; DNA binding
Biological process: DNA-templated transcription; positive regulation of transcription by RNA polymerase II; transcription by RNA polymerase II; cell differentiation; liver development; regulation of transcription by RNA polymerase II; regulation of DNA-templated transcription
Cellular component: chromatin; nucleus
Genetic constraint (gnomAD): Loss-of-function variants: 8 observed, 5.31 expected, observed/expected ratio (o/e) 1.51, 90% interval 0.83 to 1.93. That is too few expected variants to judge how well the gene tolerates losing a copy. Missense variants: 406 observed, 281.83 expected, observed/expected ratio (o/e) 1.44, 90% interval 1.33 to 1.56. Synonymous variants: 216 observed, 143.35 expected, observed/expected ratio (o/e) 1.51, 90% interval 1.35 to 1.69.
Homologues: Orthologues: chimpanzee NKX2-8 (99% identical), macaque NKX2-8 (95% identical), rabbit NKX2-8 (90% identical), dog NKX2-8 (87% identical), pig NKX2-8 (86% identical), rat Nkx2-8 (76% identical), mouse Nkx2-9 (75% identical), tropical clawed frog nkx2-8 (46% identical), Drosophila melanogaster scro (37% identical), Caenorhabditis elegans ceh-24 (30% identical), Caenorhabditis elegans ceh-28 (23% identical), Caenorhabditis elegans ceh-9 (20% identical), and 3 more. Paralogues in human: NKX2-2 (46% identical), NKX2-4 (38% identical), NKX2-1 (37% identical), NKX2-3 (35% identical), NKX2-5 (33% identical), NKX2-6 (33% identical), NKX3-2 (27% identical), NKX1-1 (23% identical), NKX1-2 (22% identical), NKX3-1 (21% identical), NKX6-2 (18% identical), NKX6-1 (18% identical), and 1 more.
Diseases named in the same sentence as NKX2-8 in open-access papers:
NKX2-8 is named in the same sentence as 21 diseases in open-access papers, as found by Europe PMC text mining. Sharing a sentence is not in itself a finding about the gene and the disease. The quoted sentences say what the papers report.
bladder cancer (4 papers, 2014 to 2023). "The knockdown of NKX2-8 promoted the invasion and metastatic potential of bladder cancer cells, whereas the overexpression of NKX2-8 inhibited this potential." (PMID 37627900, 2023). "The overexpression of NKX2-8 in bladder cancer T24 cells significantly inhibited cell proliferation in vitro and in vivo, whereas the silencing of Nkx2-8 in bladder cancer 5637 cells dramatically enhanced cell proliferation." (PMID 37627900, 2023). "Both the mRNA and protein expression of NKX2-8 were markedly reduced in bladder cancer tissues when compared to normal bladder tissues." (PMID 37627900, 2023). "Nkx2-8 potentially acts as a tumor suppressor gene in bladder cancer progression and could be developed as prognostic biomarker of bladder cancer." (PMID 37627900, 2023). "In bladder cancer tissues, NKX2-8 expression was inversely correlated with TWIST1 expression." (PMID 37627900, 2023). "Our previous studies have demonstrated that downregulation of NKX2-8 significantly contributed to malignant progression and development of bladder cancer and esophageal squamous carcinoma, and deletion of NKX2-8 conferred chemoresistance on epithelial ovarian cancer." (PMID 35707355, 2022). "In addition, the NKX2-8/TWIST1 axis plays a crucial role in bladder cancer EMT and may be a potential therapeutic target for bladder cancer." (PMID 37627900, 2023). "Bladder cancer patients with tumors that were NKX2-8 positive and low TWIST1 expression had better prognosis as compared to those that were negative NKX2-8 and harbored high TWIST1 expression." (PMID 37627900, 2023).
epithelial ovarian cancer (4 papers, 2020 to 2024). "The combination of perhexiline and cisplatin markedly reduced the growth of an epithelial ovarian cancer (EOC) cell line xenograft bearing a deletion in the NK2 homeobox 8 (NKX2-8+/−) gene." (PMID 37110858, 2023). "Perhexiline has been additionally shown to sensitise epithelial ovarian cancer cells to cisplatin by counteracting NKX2-8 deletion-induced platinum resistance." (PMID 37110858, 2023). "Ovarian cancer patients with low expression of the tumor suppressor NKX2–8 have a poor prognosis, with the deletion of NKX2-8 activating FAO and increasing chemoresistance." (PMID 33291682, 2020). "The loss of NKX2-8 dissembles a deacetylation complex, resulting in chromatin acetylation leading to increased CPT1-A and CPT2 expression in ovarian cancer." (PMID 33291682, 2020). "NKX2-8 deletion-reprogrammed fatty acid metabolism contributes to chemoresistance and Perhexiline may be a potential tailored treatment for patients with NKX2-8-deleted epithelial ovarian cancer." (PMID 39588377, 2024).
lung carcinoma (4 papers, 2011 to 2022). "Gain at 14q13 has been studied in relation to lung cancer, and co-amplification and overexpression of the transcription factors TTF-1, NKX2-8, and PAX9 (all located at 14q13) have been associated with cisplatin resistance in lung cancer cell lines." (PMID 21858162, 2011). "This region containing NKX2-1 and NKX2-8 genes were reported as prognostic factors in lung cancer." (PMID 35402275, 2022).
breast carcinoma (1 paper, 2022). "Taken together, our results indicate that the reduced NKX2-8 is linked to the development of bone-metastasis in breast cancer." (PMID 35707355, 2022). "The reverse correlation adverse of NKX2-8 with PTHrP expression was also demonstrated using IHC analysis in breast cancer tissues, which NKX2-8 expression was adversely associated with the PTHrP level." (PMID 35707355, 2022). "The expression of NKX2-8 was examined via immunohistochemistry analysis in 344 breast cancer tissues." (PMID 35707355, 2022). "Overall, the present data provided in current study suggest a potential therapeutic application of PTHrP inhibitors for treatment and prevention of downregulation of NKX2-8-induced breast cancer bone metastasis." (PMID 35707355, 2022). "A bone-metastatic mouse model was used to examine the effect of NKX2-8 dysregulation on breast cancer bone metastasis and the impact of three PTHrP inhibitor on prevention of breast cancer bone metastasis." (PMID 35707355, 2022). "Collectively, these results demonstrated the NKX2-8 specifically inhibits bone metastasis of breast cancer cells by reducing osteoclastogenesis." (PMID 35707355, 2022). "In this study, we observed that NKX2-8-silencing-induced PTHrP protein plays a vital role in bone metastasis of breast cancer by promoting osteoclastogenesis." (PMID 35707355, 2022). "The downregulated expression of NKX2-8 was significantly correlated with breast cancer bone metastasis." (PMID 35707355, 2022). "The biological role of NKX2-8 in breast cancer organ-specific metastasis was then examined using NKX2-8-silenced SCP-2 and NKX2-8–overexpressing MDA-MB-231 breast cancer cell lines, and then injected intracardially the corresponding cells into nude mice." (PMID 35707355, 2022). "In vivo bone-metastatic mouse model indicated that silencing NKX2-8 promoted, but overexpressing NKX2-8 inhibited, breast cancer osteolytic bone metastasis and osteoclastogenesis." (PMID 35707355, 2022). "Taken together, these results suggest that the NKX2-8/HDAC1 repressor complex is involved in NKX2-8-inhibited PTHrP expression in breast cancer cells." (PMID 35707355, 2022). "Consistently, silencing HDAC1 in the breast cancer cells significantly abolished the reductive effect of NKX2-8 on the formation of TRAP+-multinuclear osteoclasts and TRAP enzymatic activity." (PMID 35707355, 2022). "The NKX2-8-silenced breast cancer cells-injected mice exhibited earlier bone metastases, as revealed by μCT analysis, and histology examination." (PMID 35707355, 2022). "Histological TRAP staining showed that NKX2-8-overexpressing breast cancer cells significantly suppressed activation of osteoclasts." (PMID 35707355, 2022). "Importantly, our findings demonstrated that silencing NKX2-8 in breast cancer cells influenced their ability to affect the pre-metastatic niche." (PMID 35707355, 2022). "Furthermore, targeting PTHrP effectively inhibited NKX2-8-downregulation-mediated breast cancer bone metastasis." (PMID 35707355, 2022). "Our results showed that NKX2-8 plays a critical role in breast cancer bone metastasis." (PMID 35707355, 2022). "Silencing of NKX2-8 in breast cancer cells activated PTHrP transcription." (PMID 35707355, 2022). "Consequently, PTHrP derived from NKX2-8 silenced-breast cancer cells contribute to formation of pre-bone metastatic niche through alteration of RANKL/OPG ration via acting on osteoblasts, resulting in instigating osteoclastogenesis that led to metastatic bone destruction." (PMID 35707355, 2022). "Taken together, our results uncover a novel mechanism underlying NKX2-8 downregulation-mediated breast cancer bone metastasis and represent that the targeting PTHrP might be a tailored treatment for NKX2-8 silencing-induced breast cancer bone metastasis." (PMID 35707355, 2022).
breast carcinoma (continued). "Among them, NKX2-8 levels were found to be significantly decreased in bone-metastatic tissues compared to normal breast tissues, or non-metastatic breast cancer tissues, respectively." (PMID 35707355, 2022). "Mechanistically, NKX2-8 directly interacted with HDAC1 on the PTHrP promoter, which resulted in a reduction of histone H3K27 acetylation, consequently transcriptionally downregulated PTHrP expression in breast cancer cells." (PMID 35707355, 2022). "Conversely, silencing NKX2-8 drastically increased, but overexpressing NKX2-8 decreased, the enrichment of H3K27 acetylation (H3K27ac) on the promoter of PTHrP gene in breast cancer cells, which demonstrated that NKX2-8 inhibited PTHrP expression via HDAC1 to reduce H3K27ac on the promoter of PTHrP." (PMID 35707355, 2022). "Moreover, we found that treatment with all three PTHrP inhibitor exhibited dramatic blocked effect on vicious cycle induced by silencing NKX2-8, as indicated by decreased level of bone matrix-released TGF-β1 and slower growth rates of breast cancer cells." (PMID 35707355, 2022). "Furthermore, ChIP assays revealed that downregulation of NKX2-8 significantly reduced, whereas upregulation of NKX2-8 enriched, the HDAC1 level on the PTHrP promoter in breast cancer cells." (PMID 35707355, 2022). "Specifically, NKX2-8 interacts with HDAC1 to form a complex that suppresses PTHrP transcription in breast cancer cells with no bone metastasis, while silencing NKX2-8 could eliminate its inhibition of bone metastasis." (PMID 35707355, 2022). "Moreover, the NKX2-8 silencing-promoted vicious cycle was significantly blocked by silencing PTHrP, as indicated by downregulation of bone matrix-released TGF-β and reduced growth rates of breast cancer cells." (PMID 35707355, 2022). "Herein, we demonstrated that NKX2-8 transcriptionally downregulated the PTHrP expression through directly interacting with histone deacetylase 1 (HDAC1) on the PTHrP promoter, resulting in a reduction of histone H3K27 acetylation, which transcriptionally downregulated PTHrP level in breast cancer." (PMID 35707355, 2022).
colon cancer (1 paper, 2021). "In colon cancer and hepatocarcinoma cell lines, SMYD3 forms transcription complexes with HSP90 and RNA polymerase II to promote H3K4 methylation and regulate the transcription of the target gene NK2homeobox8 (Nkx28), promoting tumor cell proliferation." (PMID 34335697, 2021).
Diabetes mellitus type 2 (1 paper, 2022). "Diabetes mellitus type 2 was significantly enriched in the Clinvar database and NK2 Homeobox 8 (NKX2-8, human) was enriched in the JASPAR database." (PMID 35432190, 2022).
spina bifida (1 paper, 2013). A congenital neural tube defect in which vertebrae are not fully formed. "Mutations in NKX2-8 were subsequently documented in human patients with a generally similar NTD termed spina bifida." (PMID 23874236, 2013). "The exons of NKX2-8 were sequenced in human patients with spina bifida and rare variants (rs61755040 and rs10135525) were found to be significantly over-represented (p = 0.036)." (PMID 23874236, 2013). "Additionally, rare missense variants in NKX2-8 were identified in 4% of the cases in a cohort of spina bifida patients." (PMID 23874236, 2013).
tumor (8 papers, 2014 to 2024). "Nkx2.8 (Nk2 homeobox 8) is a novel member of the NK-2 gene family, which has been involved in tumor progression and metastasis in a variety of cancers." (PMID 24678995, 2014). "Moreover, patients with negative NKX2-8 expression had a higher tumor recurrence risk as compared to those with positive NKX2-8 expression." (PMID 37627900, 2023). "Taken together, our results strongly indicated a critical role of the NKX2-8/PTHrP/RANKL axis in the regulation of osteoclastogenesis in vivo, which resulted in a vicious cycle between tumor cells and osteoclasts." (PMID 35707355, 2022).
cancer (3 papers, 2014 to 2022). A tumor composed of atypical neoplastic, often pleomorphic cells that invade other tissues. "Nkx2.8 (Nk2 homeobox 8) is a novel NK-2 gene family member that has been implicated in the progression of human cancer." (PMID 24678995, 2014). "Our results provided a new paradigm for NKX2-8 in cancer, especially in bone metastasis, in which it was involved in reshaping the bone microenvironment for and enhance metastasis." (PMID 35707355, 2022). "Human Nk2 homeobox 8 (NKX2-8), a NK2-related transcription factor, was reported to be downregulated in multiple tumors, which contributed to initiation, progression and development of cancer." (PMID 35707355, 2022).
NKX2-8 also shares sentences with these, for which no sentence is quoted: bladder urothelial carcinoma (1 paper); bone metastasis (1); esophageal cancer (1); hepatocellular carcinoma (1); liver cancer (1); liver cirrhosis (1); lumbosacral myelomeningocele (1); lymph node metastasis (1); metastasis (1); neural tube defect (1); non-small cell lung carcinoma (1); ovarian cancer (1).